BABAM1 (BRISC and BRCA1 A complex member 1)
Description:
Component of the BRCA1-A complex, a complex that specifically recognizes 'Lys-63'-linked ubiquitinated histones H2A and H2AX at DNA lesions sites, leading to target the BRCA1-BARD1 heterodimer to sites of DNA damage at double-strand breaks (DSBs). The BRCA1-A complex also possesses deubiquitinase activity that specifically removes 'Lys-63'-linked ubiquitin on histones H2A and H2AX. In the BRCA1-A complex, it is required for the complex integrity and its localization at DSBs. Component of the BRISC complex, a multiprotein complex that specifically cleaves 'Lys-63'-linked ubiquitin in various substrates. In these 2 complexes, it is probably required to maintain the stability of BABAM2 and help the 'Lys-63'-linked deubiquitinase activity mediated by BRCC3/BRCC36 component. The BRISC complex is required for normal mitotic spindle assembly and microtubule attachment to kinetochores via its role in deubiquitinating NUMA1. Plays a role in interferon signaling via its role in the deubiquitination of the interferon receptor IFNAR1; deubiquitination increases IFNAR1 activity by enhancing its stability and cell surface expression. Down-regulates the response to bacterial lipopolysaccharide (LPS) via its role in IFNAR1 deubiquitination.
Synonyms: C19orf62; MERIT40; NBA1; HSPC142; FLJ20571
Tractability: Small molecule: a structure with a bound ligand is known. PROTAC: ubiquitination databases record sites on it; its protein half-life has been measured.
Gene: Protein-coding gene on chromosome 19 (17,267,343 to 17,281,249, forward strand). Ensembl gene ENSG00000105393.
Subcellular location: Cytoplasm; Nucleus
Subcellular location (Human Protein Atlas): Nuclear bodies; Cytosol; Nucleoplasm
Pathways (Reactome):
DNA Repair: Nonhomologous End-Joining (NHEJ); Processing of DNA double-strand break ends; Recruitment and ATM-mediated phosphorylation of repair and signaling proteins at DNA double strand breaks
Cell Cycle: G2/M DNA damage checkpoint
Metabolism of proteins: Metalloprotease DUBs
Gene Ontology:
Molecular function: identical protein binding; protein binding
Biological process: DNA repair-dependent chromatin remodeling; double-strand break repair; mitotic G2 DNA damage checkpoint signaling; positive regulation of DNA repair; response to ionizing radiation; mitotic G2/M transition checkpoint; regulation of DNA repair; response to vitamin B6
Cellular component: BRCA1-A complex; BRISC complex; cytoplasm; nuclear body; nucleoplasm; nucleus; cytosol
Genetic constraint (gnomAD): Loss-of-function variants: 15 observed, 34.38 expected, observed/expected ratio (o/e) 0.44, 90% interval 0.29 to 0.67. The upper end of that interval is the gene's LOEUF score, 0.67, which puts it in group 2 of 6, group 1 being the genes least tolerant of losing a copy. Missense variants: 393 observed, 427.56 expected, observed/expected ratio (o/e) 0.92, 90% interval 0.85 to 1. Synonymous variants: 169 observed, 160.3 expected, observed/expected ratio (o/e) 1.05, 90% interval 0.93 to 1.2.
Homologues: Orthologues: chimpanzee BABAM1 (99% identical), macaque BABAM1 (99% identical), pig BABAM1 (96% identical), dog BABAM1 (95% identical), guinea pig BABAM1 (92% identical), mouse Babam1 (91% identical), rat Babam1 (88% identical), tropical clawed frog babam1 (71% identical), zebrafish babam1 (67% identical).
Diseases named in the same sentence as BABAM1 in open-access papers:
BABAM1 is named in the same sentence as 26 diseases in open-access papers, as found by Europe PMC text mining. Sharing a sentence is not in itself a finding about the gene and the disease. The quoted sentences say what the papers report.
breast carcinoma (15 papers, 2011 to 2025). "Based on the genetic screening of clinical cases and the results of high-throughput gene sequencing, the single nucleotide polymorphisms caused by the nucleotide sequence mutation of BABAM1 on the chromosome had a great correlation with the incidence of breast cancer." (PMID 36457747, 2022). "They detected significant associations of some haplotypes of BABAM1, ATM, CTIP (RBBP8), TOPBP1, BRIP1, BRE and RAD50 with the modification of breast cancer risk." (PMID 30823486, 2019). "It implies BABAM1 plays a role in the occurrence and progression of breast cancer." (PMID 36457747, 2022). "For example, not simply the BABAM1 gene but an extra 38 base pairs of its 5′ untranslated region is associated with increased breast cancer risk." (PMID 26472073, 2015). "Similarly, the posterior probability at the BABAM1 locus included a large number of SNPs that we could not narrow effectively based on the breast cancer association." (PMID 26472073, 2015).
ovarian carcinoma (4 papers, 2017 to 2025). A malignant neoplasm originating from the surface ovarian epithelium. "GT haplotypic structure of rs4808075‐rs8170 variants on BABAM1 gene is associated with both breast and ovarian cancers in European population." (PMID 39031745, 2024). "BABAM1 has previously been implicated as a low-penetrance risk locus that interacts with BRCA1 in both triple-negative breast cancer and ovarian cancer risk." (PMID 40775447, 2025). "The authors suggested that BABAM1 was acting as the causal gene to modify breast and ovarian cancer risk based upon its physical interaction with the BRCA1 protein complex and its expression in ovarian cancer." (PMID 36859531, 2023). "The gene expression results showed that the BABAM1 gene expression is significantly different from adjacent normal tissues in breast and ovarian cancer." (PMID 39031745, 2024).
triple-negative breast carcinoma (4 papers, 2013 to 2025). An invasive breast carcinoma which is negative for expression of estrogen receptor (ER), progesterone receptor (PR), and human epidermal growth factor receptor 2 (HER2). "In addition, BABAM1 has emerged as a significant low-penetrance risk locus for triple-negative breast cancer in genome-wide association studies as will be discussed further below." (PMID 24025454, 2013). "Variants at the BABAM1 locus, encoding a BRCA1 binding partner also known as MERIT40, have been specifically associated with triple-negative breast cancer and serous epithelial ovarian cancer, which resembles the picture seen with BRCA1 mutations." (PMID 24025454, 2013).
lung carcinoma (3 papers, 2022 to 2025). "Notably, one of the genes targeted by this shRNA construct is Babam1, which is known to increase the metastatic capability of a murine Kras-mutant lung cancer-derived cell line." (PMID 35983994, 2022). "We highlight several isoTWAS associations that demonstrate GWAS colocalization at the isoform level but not at the gene level, including CLPTM1L (lung cancer), LAMC1 (colorectal), and BABAM1 (breast)." (PMID 40775447, 2025).
schizophrenia (1 paper, 2013). A major psychotic disorder characterized by abnormalities in the perception or expression of reality. "The identified polymorphisms and the corresponding genes NR2F6, USHBP1 and BABAM1 have not previously been associated with schizophrenia or other neuropsychiatric disorders." (PMID 23805179, 2013). "Elucidating the specific mechanisms of NR2F6, USHBP1 and BABAM1 in the regulation of neurodevelopment and synaptic (re)organization could improve our conceptual framework of processes related to hippocampal volume reduction and facilitate a better understanding of schizophrenia." (PMID 23805179, 2013).
cancer (8 papers, 2015 to 2025). A tumor composed of atypical neoplastic, often pleomorphic cells that invade other tissues. "We highlight CLPTM1L, LAMC1, and BABAM1 here due to previously-reported pleiotropic associations across multiple cancers." (PMID 40775447, 2025). "MtrBTN2 cancer was found to express at higher levels a significant panel of transcripts of genes involved in the DNA homologous recombination (HR) (42.Double-strand break repair), such as BABAM1, ZSWIM7, RAD51L, RAD54L, MRE11, MCM9 and TONSL." (PMID 37816387, 2023).
BABAM1 also shares sentences with these, for which no sentence is quoted: tumor (3 papers); endometrial cancer (2); prostate carcinoma (2); aneuploidy (1); breast tumors (1); ciliopathies (1); cognitive decline (1); deafness (1); gastric cancer (1); genetic disorder (1); glioma (1); infarction (1); infection (1); Intellectual disability (1); lentivirus infection (1); melanoma (1); myocardial infarction (1); testis cancer (1); thyroid cancer (1); Usher syndrome (1).